LEP (leptin)
Diseases named in the same sentence as LEP in open-access papers (continued):
Sharing a sentence is not in itself a finding about the gene and the disease.
psychosis (8 papers, 2020 to 2025). "Previous literature have shown that increased leptin levels were significantly associated with BMI, body weight, increased waist circumference, and energy intake in psychosis." (PMID 36090349, 2022). "In the present study, we found a significant upregulation of the leptin hormone in patients with psychosis, and this level further increased after 6 months of CLZ and OLZ administration, with the effect of OLZ being more prominent than that of CLZ." (PMID 41011185, 2025). "Women with psychosis presented a significantly greater increment in BMI (6 vs. 4.9, F = 4.18, p = 0.042) and leptin levels (17.45 vs. 7.78, F = 23.29, p < 0.001) than men." (PMID 35971658, 2022). "Interference in leptin signaling in the form of leptin resistance has also been seen with antipsychotic drugs such as olanzapine used to treat psychosis and other neuropsychiatric disorders." (PMID 34912298, 2021). "The observation that higher leptin levels are associated with lower RBANS scores of language performance also support the involvement of leptin in the pathophysiology of psychosis." (PMID 32547431, 2020). "On the other hand, a recent meta-analysis revealed that impaired appetite regulation, in terms of elevated insulin levels and decreased leptin levels, occurs in early psychosis, before antipsychotic treatment." (PMID 32033608, 2020). "Martorell and colleagues, in their study published in 2019, detected increased leptin levels in the early stages of psychosis." (PMID 32033608, 2020). "In summary, this study provides additional evidence of impaired adipoinsular axis, in terms of low leptin and high insulin levels, in early psychosis." (PMID 32547431, 2020). "Serum leptin levels were found to be higher in patients with psychosis than in controls." (PMID 41011185, 2025). "Impaired leptin signaling might also be related to the pathophysiology of psychosis." (PMID 32547431, 2020). "Interestingly, even in the first episode of psychosis, before initiation of antipsychotic drugs, affected subjects experience impaired appetite regulation in terms of significantly elevated insulin and decreased leptin levels, possibly correlating with negative emotional feelings." (PMID 36979648, 2023).
pulmonary arterial hypertension (8 papers, 2014 to 2024). Pulmonary arterial hypertension (PAH) is a group of diseases characterized by mean pulmonary artery pressure >20 mmHg and elevated pulmonary arterial resistance leading to right heart failure. "We depleted endogenous oestrogen in leptin-deficient (ob/ob) mice with the oestrogen inhibitor anastrozole (ANA) and determined the effects on the development of pulmonary hypertension, plasma oestradiol and urinary 16α-hydroxyestrone (16αOHE1)." (PMID 30923189, 2019). "Upregulation of the leptin-leptin receptor axis has been shown to contribute to the pathogenesis of pulmonary arterial hypertension in humans and to experimental hypoxia-induced pulmonary hypertension in rats." (PMID 28085954, 2017). "Leptin has been determined to contribute to the occurrence of pulmonary arterial hypertension; blockage of leptin signaling reduces the severity of pulmonary hypertension." (PMID 26593914, 2015). "In patients with pulmonary arterial hypertension, there is an increase in circulating leptin which may contribute to inflammatory changes in the pulmonary circulation and thereby increase PVR." (PMID 24499246, 2014). "This suggests that leptin could play a role in modulating vasomotion directly through leptin receptor present on smooth muscle cells and therefore contribute to the progression of systemic and pulmonary hypertension in SHR." (PMID 28085954, 2017).
renal carcinoma (8 papers, 2017 to 2025). A carcinoma arising from the epithelium of the renal parenchyma or the renal pelvis. "For example, leptin, which has pro-inflammatory effects, can increase the tumorigenicity of cancer stem cells, and leptin has been associated with an increased risk of renal cancer." (PMID 37529377, 2023). "In Caki-2 primary kidney carcinoma cells, leptin increases proliferation and migration in a manner dependent on the JAK-STAT3 and ERK1/2 pathway." (PMID 33334030, 2020). "Based on this, leptin-induced signaling could play a more significant role in renal cancer progression by promoting processes such as migration and invasion related to EMT." (PMID 33334030, 2020). "In addition, leptin promotes murine renal cancer cell invasiveness through extracellular signal-regulated kinase signaling pathway, and guanosine-Rho triphosphate dependent pathways." (PMID 31534630, 2019). "Furthermore, leptin promotes the invasiveness of murine renal cancer cells via extracellular signal-regulated kinases and Rho guanosine triphosphatase dependent pathways." (PMID 29212223, 2017). "Furthermore, this might point out that versican and leptin might increase the metastatic ability of renal cancer cells." (PMID 29212223, 2017). "Therefore, leptin signaling could have a key role in renal cancer cell invasion." (PMID 31534630, 2019).
renal failure (8 papers, 2012 to 2025). "Current data show that leptin levels in CKD patients are elevated due to renal insufficiency, decreased leptin clearance in the renal circulation, and increased leptin secretion from adipose tissue." (PMID 36871015, 2023). "This might be due to the small sample size or slight change of leptin that contributed to the moderate renal insufficiency of our patients." (PMID 25649956, 2015).
thymic atrophy (8 papers, 2010 to 2022). "Experimentally, mice with leptin deficiency or leptin receptor deficiency have been shown to have thymus atrophy and poor immune response." (PMID 33907162, 2021). "The role of leptin in adaptive immunity has first evidenced working with ob/ob and db/db mice, which showed thymus atrophy, T-cell lymphopenia, and impaired delayed-type hypersensibility." (PMID 29910742, 2018). "Interestingly, among the molecular interactions involved in the control of undernutrition-induced thymic atrophy is a hormonal imbalance with a rise in glucocorticoids and a decrease in leptin serum levels." (PMID 36225882, 2022). "Indeed, DTH responses and thymic atrophy have been shown to be decreased after acute caloric deprivation and serum leptin reduction; these conditions were restored by leptin treatment." (PMID 24778633, 2014). "Leptin protects against bacterial endotoxin-induced thymic atrophy." (PMID 20546588, 2010). "Leptin also protects against bacterial endotoxin-induced thymic atrophy." (PMID 20546588, 2010).
viral hepatitis (8 papers, 2004 to 2025). An acute or chronic inflammation of the liver parenchyma caused by viruses. "However, although the role of leptin in CVH remains uncertain, there are enough data to support that leptin is an important player in viral hepatitis." (PMID 33316927, 2020). "Notably, serum LEP levels are similar in chronic viral hepatitis patients and healthy subjects point out that high serum LEP levels in NASH do not occur simply from liver damage." (PMID 33369452, 2020). "In our study, we also observed that circulating leptin levels were increased in non-alcoholic cirrhosis caused by viral hepatitis without severe energy malnutrition state." (PMID 15387890, 2004). "Subgroup analysis identified possible sources of heterogeneity, whereas meta-regression confirmed that only the presence or absence of viral hepatitis was the source of high heterogeneity among leptin-related studies." (PMID 40607220, 2025). "Another important finding of our study is that in patients with chronic viral hepatitis, high baseline serum leptin levels represent a negative prognostic factor for response to antiviral therapy." (PMID 17540037, 2007).
alcoholic fatty liver disease (7 papers, 2016 to 2024). Lipid infiltration of the hepatic parenchymal cells that is due to alcohol abuse. "Although Pcal therapy elevated cardiac adiponectin levels in apolipoprotein-E deficient mice, it showed limited effects on hepatic adiponectin and leptin levels, as well as the expression of their receptors, PPARα, PPARγ, and SREBP-1 in rats with non-alcoholic fatty liver disease." (PMID 38139208, 2023).
arteriosclerosis (7 papers, 2007 to 2024). A vascular disorder characterized by thickening and hardening of the walls of the arteries. "Altered levels of adipocytokines, such as leptin or adiponectin secreted from excess adipose tissue as a consequence of adult weight gain or weight fluctuation, may be pathogenically involved in the risk factors' clustering or arteriosclerosis directly." (PMID 17827860, 2007). "Leptin has demonstrated effects that promote inflammation, thrombosis, arteriosclerosis, and angiogenesis." (PMID 38397015, 2024). "Alamandine showed opposing actions with respect to arteriosclerosis: alamandine suppressed sympathetic nerves through the reduction of leptin secretion but induced cytotoxic signal transduction in AT." (PMID 28591164, 2017). "However, the activation of sympathetic nerves increases blood pressure, and the net effect of leptin is the induction of arteriosclerosis." (PMID 28591164, 2017). "Thus, the contribution of leptin suppression to arteriosclerosis may be low." (PMID 28591164, 2017).
autonomic dysfunction (7 papers, 2012 to 2025). "The adipokine leptin is associated with autonomic dysfunction, and may be stronger among those with higher levels of adiposity." (PMID 26983644, 2016). "Significant differences across HD cohorts in one study detected extreme effect sizes in leptin from before (ie, preHD) to after clinical motor diagnosis and interpreted findings as support for autonomic dysfunction manifested in an absence of nocturnal dipping of arterial blood pressure." (PMID 41081429, 2025).
Barrett esophagus (7 papers, 2007 to 2025). Esophageal lesion lined with columnar metaplastic epithelium which is flat or villiform. "We suggest that Forkhead transcription factors are important nuclear targets of leptin and acid mediated Akt activation in Barrett's oesophagus." (PMID 17559672, 2007). "To further characterise the downstream effectors of Akt activation in Barrett's oesophagus we examined the effects of acid and leptin on the phosphorylation of the pro-apoptotic protein Bad and the FKHR transcription factor FOXO1." (PMID 17559672, 2007). "A recent epidemiological study reported that male patients with Barrett's oesophagus had significantly higher leptin levels than BMI-matched controls, but no such association was seen for women." (PMID 20550712, 2010). "Similarly, increased leptin levels have been shown to be associated with increased risk of Barrett’s oesophagus in males, independent of adiposity." (PMID 25706622, 2015). "Intervention trials in inactive, overweight adults without Barrett’s oesophagus have also observed significant reductions in leptin following exercise, with these reductions largely mediated by reductions in adiposity." (PMID 25706622, 2015).
cervical cancer (7 papers, 2016 to 2023). A primary or metastatic malignant neoplasm involving the cervix. "High ObR expression is correlated with poor outcomes in women with cervical cancer, whereas high leptin levels are associated with favorable outcomes." (PMID 37509120, 2023). "Interestingly, they found that leptin was positively correlated with a higher grade of cervical carcinoma along with an increased expression of c-myc and bcl-2 antiapoptotic genes." (PMID 37509120, 2023). "Moreover, further studies are necessary to better elucidate the role of leptin in cervical carcinoma." (PMID 37509120, 2023). "Moreover, the same authors performed a study assessing leptin levels in 80 patients with cervix carcinoma." (PMID 37509120, 2023). "Thus, the authors demonstrated that leptin plays a role in cervical carcinoma growth and progression." (PMID 37509120, 2023). "In cancer, the silencing of leptin in HeLa cells, a cervical cancer cell line, has reduced the expression of bcl-2 and, consequently, promotes apoptosis and inhibits cell proliferation, thus suggesting the probable role of leptin in the progression of cervical cancer." (PMID 36555171, 2022). "Similarly, expression levels of leptin correlated positively with the grades of cervical carcinoma as well as expression of c-myc and bcl-2, indicating the regulatory roles of leptin in cell proliferation and apoptosis in cervical cancer cells." (PMID 27185268, 2016). "Both leptin and OB3 peptides induced phosphorylation of ERK1/2 and PI3K and phosphorylation of Ser-727 and Tyr-705 of STAT3 in human cervical cancer HeLa cells." (PMID 28750624, 2017).
cholangiocarcinoma (7 papers, 2012 to 2023). A carcinoma that arises from the intrahepatic biliary tree (intrahepatic cholangiocarcinoma) or from the junction, or adjacent to the junction, of the right and left hepatic ducts (hilar cholangiocarcinoma). "Moreover, loss of leptin function suppressed the development of cholangiocarcinoma." (PMID 33167521, 2020). "Leptin stimulates the proangiogenic capability of cholangiocarcinoma cells through the miR-122/PKM2 axis." (PMID 37686525, 2023). "Regarding cholangiocarcinoma, leptin was found to increase the proliferation and metastatic potential of cholangiocarcinoma cells through STAT3-dependent activation of ERK 1/2." (PMID 33167521, 2020). "Leptin treatment increases the growth and migration of cholangiocarcinoma cells in vitro and cholangiocarcinoma is inducible in obese fa/fa Zucker (faulty ObR) rats." (PMID 22263109, 2012). "RiskScore of cholangiocarcinoma patients with 10 genes calculated followed the formula: The RiskScore=0.429*VEGFC -0.434*NFKBIA-0.884*NLRX1+0.54*AKT1+0.629*CSRP1+0.406*EPO+0.833*IL31RA+1.023*LEP+0.341*MUC4+0.363*SEMA4B." (PMID 36817485, 2023). "In human cholangiocarcinoma cell lines SK-ChA-1 and TFK-1, leptin stimulates EMT by stimulating cell migration and invasion, decreasing in E-cadherin and β-catenin expression, and increasing vimentin and, N-cadherin expression as well as the proangiogenic capability through the miR-122/PKM2 axis." (PMID 33334030, 2020).
deficient (7 papers, 2008 to 2022). "Leptin has been shown to regulate GH secretion and serum leptin levels have been associated with circulating IGF-1 and IGFBP-3 levels in normal and GH-deficient humans." (PMID 19017403, 2008).
eosinophilia (7 papers, 2012 to 2025). "We found that leptin levels are related to eosinophilia in both peripheral blood and NPs, and are also related to the severity of ECRS." (PMID 35046816, 2021). "Nevertheless, in naïve BALB/cBALB/c mice just a small eosinophilia of about 2 × 105 eosinophils per cavity (similar magnitude observed in naïve C57BL/6 mice) was observed at sites of leptin administration (0.5, 1, or 2 mg/kg; i.pl)." (PMID 33117286, 2020). "Expression of leptin and osteopontin (OPN) proteins in serum was detected, and correlation analysis with eosinophilia was performed." (PMID 30473626, 2018). "We found that upregulated serum and nasal leptin and OPN expression in AR were positively correlated with eosinophilia and eosinophil cationic protein levels." (PMID 30473626, 2018). "Thus, both leptin and possibly eotaxin could contribute to relative eosinophilia in the obese." (PMID 23509614, 2013). "Obese patients tend to exhibit higher leptin levels and blood neutrophilia but not eosinophilia in blood or sputum, nor sputum neutrophilia." (PMID 40978164, 2025). "Of note, and precisely as observed here for leptin, PGD2’s ability to induce local eosinophilia in BALB/c mice also depends on specific experimental strategies to create a proper PGD2-sensitive environment, such as the sensitization of BALB/c mice protocol employed elsewhere and here." (PMID 33117286, 2020). "Unfortunately, we do not have data on leptin, adiponectin, and eotaxin to further support their role in the observed eosinophilia." (PMID 23509614, 2013).
esophageal cancer (7 papers, 2013 to 2025). A primary or metastatic malignant neoplasm involving the esophagus. "Akt protein kinase is critical for the pro-growth and anti-apoptotic effects of leptin in esophageal cancer cells, and atorvastatin inhibits esophageal carcinogenesis by reducing the leptin-induced activation of Akt." (PMID 40002387, 2025). "Of the angiogenic factors VEGF, Angiopoietin-2, PECAM-1, Follistatin, Leptin, G-CSF, HGF, PDGF-BB and IL-8, two angiogenic factors (HGF and Follistatin) are associated with esophageal cancer patients’ prognosis in posttherapeutic tumor tissue." (PMID 25885021, 2015).
insulinoma (7 papers, 2004 to 2023). "In this study, we characterise the regulation of inflammation-related genes by leptin in insulinoma cells and compare the effect of transcriptional regulation by leptin with that of other cytokines." (PMID 17521427, 2007). "In the present study we used rat RINm5F insulinoma cells as a model system to study the changes in gene expression that leptin elicits in β-cells and to characterise the signalling pathway(s) by which the transciptional effects of leptin are mediated." (PMID 17521427, 2007). "To address the question whether the regulation of these promoters by leptin was a specific feature of insulinoma cells, we took advantage of a LEPRb-expressing PC-12 pheochromocytoma cell line that was established in a previous study." (PMID 17521427, 2007). "We have used RINm5F insulinoma cells as a model system for a peripheral target cell of leptin." (PMID 17521427, 2007). "We have assessed whether one of these analogues, the aminoguanidine carboxylate BVT.12777, opens KATP channels in rat insulinoma cells, by the same mechanism as leptin." (PMID 15329154, 2004). "In addition, leptin was able to induce inflammation-related genes in RINm5F insulinoma cells." (PMID 35628332, 2022). "The main result of our study is that leptin induces the expression of inflammation-related genes in RINm5F insulinoma cells, of which only PAP was already known as a leptin target gene." (PMID 17521427, 2007). "In rat islet cells and in rodent insulinoma cell lines (RINm5F, MIN6), leptin has been shown to stimulate tyrosyl phosphorylation of STAT1, STAT3, STAT5 and dual phosphorylation of the MAP kinases ERK1/2." (PMID 17521427, 2007). "Leptin was found also to stimulate PI3K in different tissues and organs such as HepG2 cells, pancreatic β cells, fibroblasts, macrophages, C2C12 muscle cells and insulinoma cells." (PMID 24340098, 2013). "This study shows that BVT.12777, like leptin, activates KATP channels in insulinoma cells." (PMID 15329154, 2004).